FOXL2 (forkhead box L2)
Diseases named in the same sentence as FOXL2 in open-access papers (continued):
Sharing a sentence is not in itself a finding about the gene and the disease.
granulosa cell tumor (continued). "The absence of FOXL2 variant does not favor the diagnosis of luteinized granulosa cell tumor." (PMID 38136408, 2023). "Moreover, some authors consider that the presence of a FOXL2 variant favors the diagnosis of adult granulosa cell tumors rather than thecomas." (PMID 38136408, 2023). "By definition, sex cord–stromal tumors NOS usually display no DICER1 nor FOXL2 variant since they may represent a distinct entity rather than a subgroup of adult granulosa cell tumors or SLCTS, although one case with DICER1 variant and few cases with FOXL2 variants have been reported." (PMID 38136408, 2023). "In practice, in the case of an unusual morphology such as luteinized cells, the molecular pathology may help to rule out differential diagnoses: FOXL2 variant would favor a luteinized adult granulosa cell tumor while DICER1 variants could be seen in juvenile granulosa cell tumors." (PMID 38136408, 2023). "Considering this shared role between FOXL2 and RUNX1 in granulosa cell gene regulation, it is possible that Runx1 misexpression contributes to granulosa cell tumors as well." (PMID 36430923, 2022). "As FOXL2 is highly expressed in ovarian granulosa cells and plays pivotal roles in ovarian development, the interaction of FOXL2 with XRCC5 and XRCC6 was examined in human ovarian granulosa cell tumour-derived KGN cells." (PMID 32332759, 2020). "In sex cord stromal tumors, FOXL2 was expressed in 66 and 50% of adult granulosa cell tumor (AGST) and juvenile granulosa cell tumor (JGCT), respectively." (PMID 32677969, 2020). "We found that ovarian tumors from TGFBR1-CAAcre mice were immunoreactive for FOXL2, FOXO1, and INHA, supporting the development of granulosa cell tumors in these mice." (PMID 27344183, 2016). "By contrast, COV434, another granulosa cell tumor-derived cell line, has a wildtype FOXL2 genotype and does not express FOXL2 from a juvenile GC tumor, making it a better model for investigating these aspects." (PMID 37681921, 2023). "Leydig cells intensely and diffusely express calretinin, inhibin, MelanA, and CD99 while FOXL2 is usually not expressed, which allows their distinction from luteinized cells of adult granulosa cell tumors that express FOXL2." (PMID 38136408, 2023). "Other alterations are fairly specific to subtypes of non-epithelial ovarian tumors, including the recurrent FOXL2 and common DICER1 mutations in adult granulosa cell tumors and Sertoli–Leydig cell tumors, respectively." (PMID 32485873, 2020). "The recent studies provided powerful evidences that fork head box protein L2 (FOXL2), PI3K/AKT signaling pathway, TGF-β signaling pathway, Notch signaling pathway and etc. were involved in granulosa cell tumor through influencing cell proliferation and apoptosis." (PMID 29409506, 2018). "Aberrant ovarian granulosa cell proliferation and apoptosis may lead to granulosa cell tumors (GCT), the pathogenesis of which involves transcription factors GATA4, FOXL2, and SMAD3." (PMID 24416423, 2014). "For pathologists, the main purpose of molecular biology in this case would be to rule out sex cord tumors, particularly adult granulosa cell tumors and SLCTS, by searching for FOXL2 and DICER1 variants in the case of fibroma with minor sex cord elements and/or ambiguous reticulin stain." (PMID 38136408, 2023).
Blepharophimosis (44 papers, 2007 to 2026). A fixed reduction in the vertical distance between the upper and lower eyelids with short palpebral fissures. "Human mutations in FOXL2 cause blepharophimosis, ptosis, epicanthus and inversus syndrome (BPES), which can be associated with primary ovarian insufficiency, and is indirectly linked with differences of sex development (DSD)." (PMID 40102860, 2025). "FOXL2 [MIM:605597] has been identified as the causative gene for blepharophimosis, ptosis, and epicanthus inversus syndrome [MIM:110100]." (PMID 40410591, 2025). "Foxl2 was first studied in Homo sapiens, in which Foxl2 mutation causes blepharophimosis-ptosis-epicanthus inversus syndrome (BPIS) and premature ovarian failure." (PMID 35053111, 2022). "Patient ID 123 presented a genetic variant in FOXL2 inherited from the father who also presented Blepharophimosis, Ptosis, and Epicanthus Inversus syndrome (BPES) as the proband." (PMID 35885957, 2022). "67% to over 80% patients were detected mutation-positive in FOXL2 gene after clinical diagnosis based upon four typical eyelid features: blepharophimosis, ptosis, epicanthus inversus, and telecanthus." (PMID 34711234, 2021). "The blepharophimosis–ptosis–epicanthus inversus syndrome (BPES) is a rare autosomal dominant disease mainly caused by FOXL2 variants." (PMID 33796131, 2021). "The following study is a case report of a Polish family diagnosed with blepharophimosis, ptosis, and epicanthus inversus syndrome type 1 associated with c.223C > T p.(Leu75Phe) mutation in the FOXL2 gene." (PMID 31366388, 2019). "FOXL2 is an evolutionally conserved transcription factor, and its mutations cause blepharophimosis, ptosis, and epicanthus inversus syndrome (BPES), wherein affected females display eyelid defects and premature ovarian failure (POF)." (PMID 27414805, 2016). "Haploinsufficiency of the FOXL2 transcription factor in humans causes Blepharophimosis/Ptosis/Epicanthus Inversus syndrome (BPES), characterized by eyelid anomalies and premature ovarian failure." (PMID 26134413, 2015). "Instead enhancer loss occurs in Léri-Weill syndrome and BPES (Blepharophimosis, ptosis, epicanthus inversus syndrome), in which deletions of SHOX (Léri-Weill) or FOXL2 (BPES) enhancers are reported." (PMID 25701871, 2015). "FOXL2 mutations cause blepharophimosis-ptosis-epicanthus inversus syndrome (a complex eyelid malformation) and in some patients lacrimal duct anomalies, amblyopia, strabismus, and refractive errors." (PMID 22022403, 2011). "The purpose of this study was to identify the mutation(s) or deletion(s) of the forkhead box protein L2 (FOXL2) gene in Chinese patients with blepharophimosis-ptosis-epicanthus inversus syndrome (BPES)." (PMID 21321671, 2011). "The FOXL2 forkhead transcription factor is expressed in ovarian granulosa cells, and mutated FOXL2 causes the blepharophimosis, ptosis and epicanthus inversus syndrome (BPES) and predisposes to premature ovarian failure." (PMID 20209145, 2010). "Mutations in FOXL2 cause the blepharophimosis, ptosis and epicanthus inversus syndrome (BPES MIM 110100) either with (Type I) or without (Type II) premature ovarian failure." (PMID 20209145, 2010). "In humans, FOXL2 mutations cause blepharophimosis, ptosis, epicanthus and inversus syndrome (BPES)." (PMID 40102860, 2025). "Heterozygous intragenic variants of FOXL2 accounted for 71% of patients with blepharophimosis-ptosis-epicanthus inversus syndrome (BPES), which is a dominant condition characterized by eyelid and mild craniofacial defects associated with POI (type I) or not (type II)." (PMID 36793102, 2023). "FOXL2 mutations in human cause Blepharophimosis, ptosis, and epicanthus inversus syndrome (BPES)." (PMID 34711234, 2021).
Blepharophimosis (continued). "The transcription factor Foxl2 is vital to ovarian function as evidenced by the identification of mutations in the gene encoding FoxL2 that result in the condition known as blepharophimosis/ptosis/epicanthus inversus syndrome (BPES) and in some cases, premature ovarian failure (POF)." (PMID 20167115, 2010). "Loss-of-function germline mutations in FOXL2 are associated with blepharophimosis–ptosis–epicanthus–inversus syndrome [BPES;OMIM#110100]; an autosomal dominant developmental disorder characterized by eyelid malformations and premature ovarian failure due to a dysfunction of granulosa-cells." (PMID 19956657, 2009). "Moreover, a 7.4-kb cis-regulatory deletion disrupting conserved noncoding sequences and their interaction with the promoter of another FOX gene, FOXL2, mapping more than 280 kb apart, has been described as pathogenic for blepharophimosis, ptosis, and epicanthus inversus (BPES; OMIM 110100)." (PMID 25472632, 2014). "FOXL2 harbored the highest occurrence frequency (3.2%, 16/500), among whom presented with isolated ovarian insufficiency instead of blepharophimosis-ptosis-epicanthus inversus syndrome." (PMID 36793102, 2023). "Blepharophimosis, ptosis, and epicanthus inversus syndrome (BPES) is a craniofacial disorder caused by heterozygous variants of the forkhead box L2 (FOXL2) gene." (PMID 33806295, 2021). "FOXL2 is a crucially important transcription factor in granulosa cell development; an autosomal recessive disorder, blepharophimosis-ptosis-epicanthus inversus syndrome, occurring as a result of two mutant alleles of FOXL2, is associated with ovarian failure." (PMID 20069115, 2010). "FOXL2 is a gene responsible for blepharophimosis, ptosis, and epicanthus inversus and premature ovarian failure 3 under the dominant and recessive modes, and some missense variants have been seen in patients with non-syndromic premature ovarian failure (without the eye abnormalities)." (PMID 39545410, 2024). "In addition, FOXL2 mutations were reported to be associated with polycystic ovary syndrome (PCOS) and blepharophimosis-ptosis-epicanthus inversus syndrome (BPES)." (PMID 31221094, 2019).
premature ovarian failure (29 papers, 2008 to 2025). "In humans, FOXL2 also serves as an early granulosa cell marker and FOXL2 mutations have been associated with premature ovarian failure." (PMID 40580487, 2025). "Partial loss of function of the transcription factor FOXL2 leads to premature ovarian failure in women." (PMID 19538736, 2009). "Human mutations in FoxL2 can lead to premature ovarian failure or ovarian tumors." (PMID 35294875, 2022). "Mutations in the human FOXL2 gene cause eyelid malformations and premature ovarian failure." (PMID 24098544, 2013). "Mutations of FOXL2 in cases of isolated premature ovarian failure have also been reported." (PMID 22022399, 2011). "In this paper, we found that FOXL2 RNAi would upregulate StARD3 expression, suggesting that FOXL2 can inhibit StARD3 expression, reduce progesterone synthesis, and prevent premature ovarian failure." (PMID 41007402, 2025). "Mutations in the forkhead box L2 (FOXL2) gene cause 2 types of BPES distinguished by the presence (type I) and absence (type II) of premature ovarian failure." (PMID 32311999, 2020). "Mutations in the forkhead box L2 (FOXL2) gene cause two types of BPES distinguished by the presence (type I) and absence (type II) of premature ovarian failure (POF)." (PMID 26323275, 2015). "A study has found that after FOXL2 mutation in mice, the promotion of SIRT1 is lost, accelerating follicular development and activating a large number of primordial follicles, leading to premature ovarian failure." (PMID 41007402, 2025). "The FOXL2 gene, located in the region (3q22.3), has a role in premature ovarian failure." (PMID 37255590, 2023). "For example, a previous study on mouse models with ovarian FOXL2 gene deletion showed that FOXL2+/− mice have a normal phenotype, FOXL2+/+ mice have a similar phenotype as patients with human blepharophimosis syndrome, and FOXL2−/− mice exhibit narrow eye slits and premature ovarian failure." (PMID 33633772, 2020). "In humans, an autosomal dominant mutation in FOXL2 has been associated with premature ovarian failure, but not sex reversal, suggesting that also in humans FOXL2 is not essential for the initial establishment of the granulosa cell population." (PMID 32224856, 2020). "In humans, heterozygous FOXL2 disruption was associated with premature ovarian failure (POF) but homozygous FOXL2 deletion patients have not been reported so far." (PMID 31690065, 2019). "FOXL2 belongs to the family of Forkhead transcription factors and is mutated in the Blepharophimosis Ptosis Epicanthus inversus Syndrome (BPES), a genetic disorder characterized by eyelid malformations often associated with premature ovarian failure." (PMID 22022399, 2011). "Autosomal dominant mutation of FOXL2 gene is also associated with blepharophimosis-ptosis-epicanthus-inversus syndrome (BPES) which manifests in two forms, BPES type II resulting in isolated craniofacial abnormalities and BPES type I additionally being accompanied by premature ovarian failure." (PMID 36869369, 2023). "Although RSPO2 ovarian localization and RSPO2 promoter studies are needed to assess a putative direct transcriptional activation of RSPO2 by FOXL2, RSPO2 can be considered as a good candidate gene for premature ovarian failure and XX sex-reversal in human." (PMID 18384673, 2008). "Female mice that lack FOXL2 (Forkhead Box L2) had a premature ovarian failure, follicles’ somatic cells failed to develop around growing oocytes." (PMID 34732186, 2021). "In humans, mutations in the FOXL2 gene cause blepharophimosis-ptosis-epicanthus inversus syndrome (BPES), a rare autosomal-dominant disorder characterized by eyelid malformations with (type I) or without (type II) premature ovarian failure." (PMID 24098544, 2013).
ovarian carcinoma (18 papers, 2009 to 2025). A malignant neoplasm originating from the surface ovarian epithelium. "This rare cancer accounts for less than 5% of diagnosed ovarian cancers and is causally associated with the FOXL2 c.402C>G, p.C134W mutation in 97% of the adult cases (AGCTs)." (PMID 39776254, 2025). "Other human ovarian cancer cell lines expressing FOXL2, such as KGN, harbor the pathognomonic FOXL2 mutation p.Cys134Trp, imposing other limitations to the recapturing of fetal ovarian development." (PMID 38178246, 2024). "While the identified incidence of germline variants was lower in FOXL2 C134W‐mutated AGCT patients than the epithelial ovarian cancer population, we believe that this association merits further prospective evaluation." (PMID 38898688, 2024). "FOXL2 mutations was found in Granulosa cell ovarian cancer case, ~5% of ovarian cancer, which functions as a DNA binding forkhead transcription factor required for granulosa cell differentiation." (PMID 32570879, 2020). "This could be explained by the fact that FOXL2 is strongly associated with granulosa cell tumours of the ovary, a subtype of ovarian cancer that was excluded from our study cohort." (PMID 24671188, 2014). "In line with a FOXL2 expression pattern in human female tissues, we found a very limited level of Foxl2 cDNA in 2 ovarian cancer cell lines (BR5 and ID8) and 1 breast cancer cell line (4T1)." (PMID 32814714, 2020). "The analysis revealed that many of the embryonic and cell development genes are fairly high expressed in ovarian cancer including FOXL2, GATA4, NR5A1, AMHR2, MAL and WIPF3." (PMID 31744494, 2019). "In the present study, we histologically analyzed the presence of local stromal cells in human ovarian cancer tissues by examining the expression of FOXL2, a marker virtually specific to ovarian stromal cells." (PMID 30304016, 2018). "In any case, our results focusing on the expression of FOXL2 support the idea that ovarian stromal cells are the origin of ovarian cancer stromal cells." (PMID 30304016, 2018). "Our finding that FOXL2-positive cells are predominant in the stroma of ovarian tumors is consistent with the results of previous studies in which hormonal activities of ovarian cancer stroma were examined." (PMID 30304016, 2018). "For two genes, RASSF1 and FOXL2, the patients who died of the ovarian carcinoma showed a statistically higher mean of methylation compared to the patients who were still alive (M-value of 6.63 vs. 4.16 for FOXL2 and 6.43 vs. 5.17, for RASSF1; p < 0.05)." (PMID 29882921, 2018). "Many aspects of the mechanisms by which disruptions in the miRNA expression or FOXL2 function lead to ovarian cancer remain poorly understood." (PMID 23641362, 2013). "In order to find suitable models to test our vaccine, we screened several tumor cell lines, and in line with FOXL2 expression restriction in female organs, we found only modest levels of Foxl2 cDNA in 2 ovarian cancer cell lines (BR5 and ID8) and 1 breast cancer cell line (4T1)." (PMID 32814714, 2020). "To evaluate whether FOXL2-positive cells in ovarian cancer stroma express these CAF markers, we performed double immunostaining on all the primary and secondary ovarian lesions." (PMID 30304016, 2018). "Thus, only the presence of plasma cells distant from tumor cells seemed to correlate with decreased proportion of FOXL2-positive cells in the ovarian cancer stroma." (PMID 30304016, 2018). "We next examined the expression of FOXL2 in the metastatic foci of the primary ovarian cancers in the lung, brain, lymph node and peritoneum, including omentum, mesentery and uterine surface, and the primary lesions of the secondary ovarian tumors of colon, rectum, stomach and pancreas origin." (PMID 30304016, 2018). "Thus, FOXL2-positive cells in ovarian cancers seemed to have the capacity to express CAF markers irrespective of cancer subtypes." (PMID 30304016, 2018).
ovarian carcinoma (continued). "Similarly, many questions remain unsettled regarding the role of FOXL2 in pediatric ovarian cancers." (PMID 23641362, 2013). "Finally, FOXL2 is related to T cell activation in ovarian cancer and promoting apoptosis." (PMID 34603282, 2021). "Therefore, FOXL2 may be used as a specific marker of ovarian local stromal cells and examining stromal cells in human ovarian cancers might provide important clues as to the origin of CAFs." (PMID 30304016, 2018). "In contrast, ovarian cancer patients with high RNA levels of SERPINE1, SULF2, FOXL2, and CARD16 live longer in comparison with ovarian cancer patients with lower levels of these RNA transcripts." (PMID 35008958, 2022). "The expression levels of FOXL2 and CARD16 were also in agreement with the survival outcomes: The PFS and OS were better in ovarian cancer patients with higher levels of these transcripts." (PMID 35008958, 2022). "Despite the excitement generated by the recent discovery of FOXL2 and DICER1 as key tumor suppressors in pediatric ovarian cancers, there is still much to be understood regarding the mechanisms by which these events lead to cancer." (PMID 23641362, 2013). "The majority of primary and secondary ovarian cancers had abundant FOXL2-positive cells in ovarian lesions whereas there were no FOXL2-positive cells in extraovarian lesions except for four peritoneal seeding cases." (PMID 30304016, 2018). "Although primary ovarian cancers contained abundant FOXL2-positive cells, there were no FOXL2-poitive cells in most metastatic sites." (PMID 30304016, 2018). "Similar to normal ovary, in primary and secondary ovarian cancers, FOXL2 was expressed by fibroblast-like spindle cells, but not by endothelial cells, vascular smooth muscles or inflammatory cells." (PMID 30304016, 2018). "Also, previously FOXL2 expression has been observed in fibroblast-like stromal cells of ovarian cancers and ovarian-type stroma in nonovarian tumors." (PMID 41042551, 2025). "The upregulation of FOXL2 (downregulated upon RBPMS knockout) has been found to suppress cervical cancer cell proliferation and facilitate the apoptosis of these cells; thus, it could be important to study the role of FOXL2 in ovarian cancer." (PMID 35008958, 2022). "Although some stromal cells of female genital tract, the pituitary gland, and fetal eyelid also express FOXL2, none of them could be a source of ovarian cancer stroma." (PMID 30304016, 2018). "Similarly, there were no FOXL2-positive cells in most of extraovarian lesions (metastatic foci) of the primary ovarian cancers." (PMID 30304016, 2018). "Therefore, circulating stem cells are highly unlikely to be the origin of FOXL2-positive CAFs in ovarian cancers." (PMID 30304016, 2018).